MDM2 (MDM2 proto-oncogene)
Diseases named in the same sentence as MDM2 in open-access papers (continued):
Sharing a sentence is not in itself a finding about the gene and the disease.
cancer (continued). "Besides, MDM2 inhibitor enhanced the antipancreatic cancer effect of USP22 overexpression." (PMID 34743406, 2022). "Interestingly, a pan-cancer RNA editing study highlighted that the 3′ UTR of the Mouse double minute 2 homolog (MDM2) oncogene underwent A-to I editing in 11 out of the 14 cancer types investigated within a region of the 3′ UTR complementary to the miR-200 “seed” region." (PMID 34282776, 2021). "Thus, the decrease in Numb in iCCA, as well as other malignancies, might be due to the overactivation of MDM2, which is frequently observed in various cancers." (PMID 34667161, 2021). "Therefore, we hypothesized that MDM2 promotes cancer cell migration by interacting with MTBP to block the MTBP and ACTN4 binding." (PMID 33809929, 2021). "Interestingly, increased mitochondrial-MDM2 levels enhance the migratory and invasive properties of cancer cells, suggesting that mitochondrial-MDM2 could also increase cancer cell aggressiveness in tumoral hypoxic areas." (PMID 33406607, 2021). "Therefore, MDM2 became an emerging target for developing cancer treatments." (PMID 34943974, 2021). "Moreover, MDM2 suppresses the migration of cancer cells and induces apoptosis of cancer cells." (PMID 34306137, 2021). "Hence, MDM2 plays a key role in the development of malignant tumors." (PMID 32994424, 2020).
cancer (continued). "In addition to resistance to EGFR-TKIs, MDM2 amplification was also confirmed to be associated with the insensitivity to radiotherapy and the hyperprogressive disease (HPD) associated with cancer immunotherapy." (PMID 32611363, 2020). "Thus, 20(S)-25-OCH3-PPD use can be beneficial in cancer treatment via targeting the MDM2 protein." (PMID 32425780, 2020). "Therefore, this potent inhibitor has been the starting point of another round of medicinal chemistry optimization that has culminated in NVP-CGM097 (highly potent and selective MDM2 inhibitor), which is a compound currently under evaluation in a phase I clinical trial for cancer patients." (PMID 32156064, 2020). "However, the exact mechanism of how MDM2 T309 G SNP affects cancer susceptibility has not yet been fully elucidated." (PMID 31970867, 2020). "However, the basis for the high MDM2 that drives MYCN expression in such cancers has been unclear." (PMID 33425720, 2020). "In addition, USP7 is also involved in the regulation of MDM2 in cancer cells." (PMID 33061808, 2020). "In conclusion, our results indicated that the MDM2/MDMX inhibitor reversed DOX resistance of human BC by activating the TAB1/TAK1/p38 MAPK pathway, suggesting that the MDM2/MDMX inhibitor in combination with chemotherapy may provide a novel therapeutic strategy for cancer treatment." (PMID 31892970, 2020). "The discovery of SNP285 in MDM2 promoter P2 has led to an elegant hypothesis potentially solving a long-standing conundrum: Why is the SNP309G-allele associated with an increased cancer risk in Asian, but not in Caucasian populations ?" (PMID 30691044, 2019). "In addition, MDM2 was significantly overexpressed in cancer samples." (PMID 30925701, 2019). "Therefore, in addition to helping understand the regulation of EGFR in cancer cells, our finding of MDM2 as a negative regulator of DYRK1A may also bear implications in the management of the conditions associated with DYRK1A overexpression." (PMID 30910997, 2019). "By delving more into the study of the cardiovascular functions of MDM2, researchers could open new avenues for the treatment and the prevention of cardiovascular diseases, even for the development of cancer treatments where cardiovascular toxicity is curtailed." (PMID 31921839, 2019).
cancer (continued). "Thus, in different types of human cancers, both MDM2 and MDM4 are frequently overexpressed." (PMID 29584707, 2018). "The convergence on SF3B1 is intriguing, in that: MDM2 splicing appears to be particularly sensitive to SF3B1 suppression, SF3B1 is the target for multiple families of naturally occurring splicing modulators and there is an elevated SF3B1 mutation rate in cancer." (PMID 29796170, 2018). "Furthermore, simultaneous presence of MDM2 inhibitor and inhibitors of molecular chaperones can stimulate partial dissociation of these multiprotein complexes allowing drug dependent apoptosis of cancer cells." (PMID 29137250, 2017). "Thus, the current Mdm2-based cancer therapy, which solely focuses on inhibition of Mdm2, may have its limitations." (PMID 28208785, 2017). "Importantly, in anti-cancer therapies that will modulate MDM2 function, it will be critical to ensure that chromatin-bound MDM2 prevents repair of therapy-induced DNA damage that results in cell death and not the emergence of resistant tumors with an increased mutational burden." (PMID 29065514, 2017). "However, it should be noted that such cancer therapeutic strategies may be complicated by the multiple roles of Mdm2." (PMID 28208785, 2017). "Indeed, an interplay of MDM2 isoforms, MDM2 expression levels, and cellular context will dictate whether genome stability or instability is the outcome of anti-cancer therapies that target MDM2." (PMID 29065514, 2017). "Therefore, MDM2 has been considered to be a potential molecular target for cancer therapy." (PMID 27004407, 2016).
cancer (continued). "Thus, the combination of such drugs may provide a stronger anti-cancer treatment efficacy than the sole use of Mdm2-inhibitors." (PMID 27183917, 2016). "Thus, in the present study, the risk of MDM2 SNP55 was assessed in a large population based study of Norwegian incident cancer cases and controls, where SNP285 and SNP309 status had been determined previously." (PMID 27624283, 2016). "Moreover, further studies estimating the effect of gene-gene and gene-environment interactions may provide a better, comprehensive understanding of the association between MDM2 SNP285 polymorphism and cancer risk." (PMID 27890964, 2016). "Although our in vitro and in vivo studies have indicated a critical role of MDM2 in JapA's anticancer activity, further investigations on the identification and validation of mechanisms using cutting-edge techniques and state-of-the-art cancer models are required." (PMID 25739118, 2015). "Based in the limited work performed on PPAR ubiquitination (as recently reviewed), we hypothesized that the ratio of MuRF2 to the substrate may regulate whether the protein was degraded in a proteasome-dependent manner, as previously reported in cancer with MDM2:PPARα ratios." (PMID 26242235, 2015). "Our study identified a new IRES RNA that interacts with MDM2 protein and regulates its stabilization, which suggested that targeting of MDM2 through disruption of MDM2 protein-RNA interaction might be a useful strategy for developing novel anti-cancer therapeutics." (PMID 25888903, 2015). "Altogether our data address SRSF1 as a critical modulator of endogenous MDM2 alternative splicing, providing necessary information in the regulation of this important oncogene and a potential therapeutic target for intervention in the myriad cancers in which MDM2-ALT1 is observed." (PMID 25845590, 2015). "A frequently cited literature review reporting aggregate data compiled from multiple studies suggested that pan-cancer MDM2 amplification rates may be as high as 7%, but the underlying studies used a varied array of methodologies and employed no standardized amplification copy number cutoffs." (PMID 25730903, 2015). "In particular, the current simulations strongly support that TAD cancer mutants can significantly modulate the unbound conformational ensembles, which could in turn disturb the balance between binding to MDM2 and CBP and further alter how the balance is regulated by multisite phosphorylation of TAD." (PMID 25897952, 2015).
cancer (continued). "Therefore, inhibiting RNA metabolism using 8AA may be an excellent treatment option for G/G SNP309 MDM2 overexpressing cancers." (PMID 26416444, 2015). "However, there is nothing reported about the possibility of MDM2 as a biomarker of cancer." (PMID 24955377, 2014). "Taken together, this study reveals a novel mechanism by which IGF-1 activates MDM2 via the mTOR pathway, and that pharmacologic inhibition of mTOR combined with chemotherapy may be more effective in treatment of a subset of cancers harboring increased MDM2 activation." (PMID 23638184, 2013). "We and others have provided evidence supporting that MDM2 could be a target for cancer therapy." (PMID 22911819, 2012). "Thus, it appears that regulation of the BER protein, Ape1 by Mdm2 exhibits a typical ubiquitin ligase mechanism, which could become deregulated during various steps leading to establishment of a cancer cell." (PMID 23208375, 2012). "Furthermore, our results suggest that ATM agonists could be used as anti-cancer agents, in part by accelerating Mdm2 destruction." (PMID 22976441, 2012). "Therefore, we propose that 25-OCH3-PPD inhibits cancer cell motility through inhibiting MDM2." (PMID 22911819, 2012). "Accordingly, MDM2 inhibition could be an effective approach toward enhancing cancer therapy." (PMID 21483692, 2011).